XIST (X inactive specific transcript)
Synonyms: NCRNA00001; DXS1089; swd66; LINC00001; DXS399E; SXI1
Gene: Long non-coding RNA gene on chromosome X (73,820,649 to 73,852,714, reverse strand). Ensembl gene ENSG00000229807.
Gene Ontology:
Molecular function: chromatin-protein adaptor activity
Biological process: chromosome localization; constitutive heterochromatin formation; random inactivation of X chromosome; dosage compensation by inactivation of X chromosome
Diseases named in the same sentence as XIST in open-access papers:
XIST is named in the same sentence as 216 diseases in open-access papers, as found by Europe PMC text mining. Sharing a sentence is not in itself a finding about the gene and the disease. The quoted sentences say what the papers report.
breast cancer (86 papers, 2009 to 2026). A primary or metastatic malignant neoplasm involving the breast. "XIST is dysregulated in breast cancer and loss of XIST is often associated with breast tumors with poor prognosis." (PMID 39546568, 2024). "PD-L1 expression was also presented to be enhanced through the loss of the lncRNA XIST expression in breast cancer, which promoted exosomal miR-503 upregulation, leading to the M1-M2 polarization of microglia and resulting in immunosuppression." (PMID 35955480, 2022). "For example, dysregulation of XIST and 53BP1 affected the survival of breast carcinoma patients with BRCA1 mutation." (PMID 36212008, 2022). "Our study provided salivary lncRNA XIST as biomarker for secondary prevention for females, similar to risk-stratified cancer screening for breast cancer." (PMID 34640640, 2021). "XIST is highly expressed in breast cancer and is closely associated with a poor prognosis and the resistance to chemotherapy." (PMID 33228517, 2020). "Low XIST expression predicts drug response in PDXs associated with a significant reduction in the breast cancer stem cells population." (PMID 28831025, 2017). "Analyses of the BRCA dataset showed that aberrant hypomethylation of X-linked genes occurred in nearly 50% of breast cancer samples with correspondingly reduced XIST expression." (PMID 25706888, 2015). "Therefore, loss of XIST in ovarian cancer cells can result in the enrichment of M-CSC with similar characteristics as in breast cancer." (PMID 39546568, 2024). "It was studied that loss of XIST could activate MSN‐c‐Met via exosomal miRNA to promote brain metastasis in breast cancer." (PMID 38680032, 2024). "The significant decrease in lncRNA XIST expression may, in part, contribute to the notably low risk of breast cancer observed in women with TS." (PMID 39630788, 2024). "For example, XIST could act as an oncogene in breast cancer and was closely associated with a poor prognosis." (PMID 35322118, 2022). "Recent studies have identified associations between aberrant XIST expression and breast cancer." (PMID 34527584, 2021). "In breast cancer cells, XIST has anti-cancer effects by regulating miR-454 or miR-362-5p, which inhibit cell proliferation and epithelial-mesenchymal transition (EMT), while also inducing apoptosis." (PMID 40308577, 2025). "Here, we suggest that decreased expression of XIST in circulating NK cells isolated from peripheral blood of breast cancer patients can decrease NK cell proliferation, reducing NK cell counts in breast cancer patients." (PMID 40781182, 2025). "Here, we show that XIST is among the downregulated lncRNAs in circulating NK cells isolated from peripheral blood of breast cancer patients with fold change 0.42, P = 0.007." (PMID 40781182, 2025). "Future research should focus on validating the cuproptosis-related gene signature in diverse cohorts and exploring the functional roles of the lncRNA XIST/miR-92b-3p/MTF1 axis in breast cancer progression." (PMID 39867656, 2024). "The expression level of lncRNA XIST was downregulated in breast cancer, and the deletion of lncRNA XIST promoted breast cancer cells metastasize to brain." (PMID 39309008, 2024). "According to the results, the blood levels of SPRY4‐IT1, XIST, and H19 lncRNAs have excellent potential in discriminating breast cancer from the healthy controls." (PMID 36274054, 2023). "There are several pathways by which XIST exerts its effect on different types of cancer such as non-small cell lung cancer, breast cancer, and colorectal cancer." (PMID 36770654, 2023). "The lncRNAs MALAT1 and XIST are two important cancer-related molecules previously studied in several breast cancer contexts." (PMID 37835376, 2023). "Here we identify XIST as a key regulator of breast cancer stem cells (CSCs), which exhibit aldehyde dehydrogenase positive (ALDH+) epithelial- (E) and CD24loCD44hi mesenchymal-like (M) phenotypes." (PMID 36922677, 2023).
breast cancer (continued). "Our study also ascertained the lncRNA XIST/miR-92b-3p/MTF1 regulatory axis for the progression of breast cancer." (PMID 36312586, 2022). "On the contrary, evidence shows that XIST is notably downregulated in breast cancer, renal cell carcinoma, and osteosarcoma." (PMID 35723009, 2022). "XIST was also suggested as a likely cancer immune marker in breast cancer patients with high PD-L1 levels." (PMID 36312586, 2022). "In human breast cancer HCC202 cells, which express a synonymous heterozygous mutation in the coding region of FOXP3, simultaneous silencing of XIST from XCI led to enhanced and prolonged FOXP3 activation." (PMID 35130925, 2022). "Recent studies have demonstrated that XIST is down-regulated in several cancers and suppresses the progression of tumors, especially breast cancer." (PMID 36212008, 2022). "There is an abnormal expression of lncRNA XIST in a variety of cancers, such as thyroid cancer, colorectal cancer, breast cancer, and oral cancer." (PMID 36035993, 2022). "As a specific expression of lncRNA in female cells, a large number of studies have shown that XIST is closely related to the high incidence of cancer in women, such as breast cancer, cervical cancer, thyroid cancer, and ovarian cancer." (PMID 36035993, 2022). "MIR29B2CHG, NEAT1, MALAT1, AC005332.4, NORAD, and XIST were elevated in normal breast samples than in breast cancer samples." (PMID 35756601, 2022). "Our research also showed that XIST expression was obviously lower than that in normal tissues from 98 breast cancer samples and its expression was negatively related to lymph node invasion and TNM stage." (PMID 36212008, 2022). "The lncRNA X-Inactive Specific Transcript (XIST) is known for its regulatory role in breast cancer brain metastases (BCBM), yet its immunostimulating functions have only recently been discovered." (PMID 34943820, 2021). "The long non‐coding RNA XIST was found to be of lower levels in breast cancer patients with brain metastasis and downregulation of XIST enhances tumour cell malignancy and induces brain metastasis in vivo." (PMID 33145869, 2021). "Depletion of XIST in breast cancer induced M1-M2 macrophage polarization of microglia, leading to promotion of immunosuppressive cytokines and blockade of T-cell proliferation." (PMID 34496886, 2021). "lncRNA XIST knockout promotes the secretion of exosomal miRNA-503 from breast cancer cells, which promotes brain metastasis by mediating microglia cell polarization." (PMID 32337272, 2020). "Many studies have documented the tumor suppressor function of XIST in breast cancer and TNBC, which is consistent with its expression pattern as revealed in this study." (PMID 33392077, 2020). "In the present study, we also observed low miR-92b and high XIST expression concurrently in breast cancer tissues and cell lines." (PMID 32143670, 2020). "miR-200c and lncRNA XIST have been reported to affect the biological functions of multiple cancer cells including gastric cancer and breast cancer cells, respectively." (PMID 29559853, 2018). "XIST has also been proposed to act as a tumor suppressor in breast cancer by regulating phosphorylated AKT, and as an oncogene in non-small cell lung cancer by downregulating the tumor suppressor KLF2." (PMID 30281678, 2018). "XIST has also been shown to interact with BRCA1, a gene frequently mutated in triple negative breast cancers (TNBC) further implicating its role in breast cancer." (PMID 29732012, 2018). "XIST can also be used as a biomarker predicting breast cancer response to HDAC inhibitors such as abexinostat." (PMID 29732012, 2018). "XIST's relationship with the breast cancer gene BRCA1 (which is a well-known tumour suppressor gene, TSG) has been widely studied." (PMID 30159409, 2016). "It has been found that BRCA1-defficient breast cancer cell lines have increased XIST expression suggesting it to be used as a marker to study tumour development." (PMID 30159409, 2016).
breast cancer (continued). "Among these, XIST is a well-known imprinted lncRNA that is abnormally expressed in ovarian and breast cancers." (PMID 26448942, 2015). "The expression of XIST RNA were also significantly lower in the paired tumor samples of this group of patients (t-test p-value < 0.01) and the overall and relapse-free survivals are lower for breast cancer patients with lower expression of XIST." (PMID 25706888, 2015). "RT-qPCR revealed that XIST was expressed at slightly lower levels in the tumor cell lines, and the associated RNA FISH signal was slightly weaker and was more dispersed in the breast cancer cell lines." (PMID 25653311, 2015). "In particular, the relationship between the breast cancer predisposing gene BRCA1 and XIST, the main mediator of X chromosome inactivation, has been intensely investigated, but still remains controversial." (PMID 19440381, 2009). "We investigated some aspects of this intricate matter by sounding out the supposed relationship between BRCA1 and XIST expression/localisation and by assessing the nuclear XIST behaviour in breast cancer cells." (PMID 19440381, 2009). "We investigated this topic by assessing XIST behaviour in different groups of breast carcinomas and in a panel of breast cancer cell lines both BRCA1 mutant and wild type." (PMID 19440381, 2009). "The function of XIST as a tumor suppressor in breast cancer has been clarified." (PMID 41459628, 2026). "Therefore, targeting vimentin and/or XIST via RNA interference should be a promising therapeutic strategy for breast cancer treatment." (PMID 40690373, 2025). "Studies of XIST's function in CSC maintenance have been conducted in breast cancer." (PMID 39546568, 2024). "As Grade 3 ovarian tumors showed low XIST expression and previous reports have shown that XIST regulates breast cancer SCs, we investigated whether ovarian tumors with low XIST expression had a more undifferentiated cellular state." (PMID 39546568, 2024). "The deletion of XIST in breast cancer can promote the phenotypic transformation of microglia through the transport of miR-503 exosomes to microglia, leading to local immunosuppression and promoting brain metastasis in breast cancer." (PMID 37178254, 2023). "In addition, 98 cases of breast cancer were also collected to assess the clinicopathological role of XIST in BRCA." (PMID 36212008, 2022). "Moreover, patients with breast cancer and with elevated XIST levels demonstrated a better survival (p = 0.00016)." (PMID 36312586, 2022). "The lncRNA X-inactive-specific transcript (XIST) was shown to harbor a tumor suppressor potential in breast cancer through its exosomal miR-503 sponging ability, where knockdown strategies of XIST revealed the promotion of malignancy and stemness through the relief of exosomal miR-503 sponging." (PMID 35955480, 2022). "Further, XIST overexpression hampered breast cancer cell progression in vitro and in vivo." (PMID 35899235, 2022). "XIST regulates breast cancer progression by targeting miRNA-182-5p." (PMID 36038831, 2022). "Furthermore, a series of lncRNAs have been elucidated to serve as important prognostic hallmarks in numerous tumors, for instance, MALAT1 in breast cancer and digestive system cancer, XIST in various solid tumors, BCAR4 and SNHG16 in diverse human neoplasms." (PMID 33639865, 2021). "XIST is highly expressed in cases of glioblastoma, breast cancer and ovarian cancer, suggesting it may be a biomarker for cancer diagnosis." (PMID 33501488, 2021). "Moreover, miR-200c-3p was reported to interact with XIST in brain microvascular endothelial cells and breast cancer cells." (PMID 34243729, 2021). "To further confirm that miR-7 directly targets XIST in breast cancer, we performed a RIP assay." (PMID 32143670, 2020). "However, the other study showed that the exosomes derived from the XIST-knockdown breast cancer cells induced the conversion of microglia from M1 to M2 phenotype in the brain metastatic lesions." (PMID 33384994, 2020).
breast cancer (continued). "Reduced expression of XIST was observed in patients with breast cancer." (PMID 32219093, 2020). "The overexpression of miR-7 and/or the knockdown of XIST may contribute to a significant approach to the treatment of breast cancer." (PMID 32143670, 2020). "In breast cancer, XIST could inhibit proliferation and migration by activating MSN-c-Met and reprogramming microglia to promote brain metastasis." (PMID 31384173, 2019). "Similar to breast cancer, our literature search uncovered several high ranked lncRNAs that are linked to blood cancers but yet not been added to the LncRNADisease database, such as MIAT, MALAT1, XIST, CRNDE." (PMID 31379598, 2019). "XIST expression is significantly reduced in breast cancer cell lines and breast cancer samples." (PMID 30046354, 2018). "Moreover, XIST can also behave as a tumor suppressor through inhibition of AKT activation in breast cancer." (PMID 29732012, 2018). "Furthermore, another lncRNA, Jpx which is also involved in the tight regulation of XIST and positively regulates it, has decreased levels in breast cancer samples." (PMID 29732012, 2018). "Some studies have indicated that XIST participates in the progression of breast cancer." (PMID 29715309, 2018). "The levels of XIST in 16 breast cancer cell lines, led to their grouping into two major classes, one is a low dose sensitive group, in which the cancer stem cells were differentiated by abexinostat and a high dose sensitive group whose cancer stem cell populations were stable." (PMID 29732012, 2018). "In breast cancer, the lncRNA XIST was significantly reduced comparing with normal breast tissue." (PMID 27732939, 2017). "However, aberrant activation of Akt induced by downregulation of XIST in breast cancer resulted in malignant progression." (PMID 29100288, 2017). "By evaluating the level of XIST lncRNA, breast cancer cell lines could be divided into a low-dose sensitive group whose cancer stem cells (CSC) were differentiated by abexinostat, and a high-dose sensitive group whose CSC population were stable." (PMID 27732939, 2017). "However, reduction of XIST level in breast cancer releases HDAC3 which can target and suppress the promoter activity of the PHLPP1." (PMID 27732939, 2017). "However, the conflicting evidences on a communication between XIST and BRCA1 prompted us to further investigate on this issue and on XIST behaviour in breast cancer cells." (PMID 19440381, 2009). "The lncRNA XIST/miR-92b-3p/MTF1 regulatory axis may be important in breast cancer progression." (PMID 36312586, 2022). "Moreover, we identified the lncRNA XIST/miR-92b-3p/MTF1 regulatory axis for breast cancer." (PMID 36312586, 2022). "Finally, serum levels of XIST could separate breast cancer patients from healthy controls with AUC value of 0.78." (PMID 34179019, 2021). "However, another study suggested the potential oncogenic role of XIST in breast cancer." (PMID 34527584, 2021). "Additionally, serum exo‐XIST levels could be served as an assessment of change in breast cancer load." (PMID 33949761, 2021). "Interestingly, XIST plays an antioncogenic role in breast cancer." (PMID 32219093, 2020). "The results revealed elevated levels of several breast cancer-related genes, including AZGP1, GATA-3, KRT14, XIST, and ESR1." (PMID 40474021, 2025). "The gene detection results demonstrated elevated levels of breast cancer-related genes, including AZGP1, GATA-3, KRT14, XIST, and ESR1." (PMID 40474021, 2025). "Aberrant expression of XIST, a long noncoding RNA (lncRNA) initiating X chromosome inactivation (XCI) in early embryogenesis, is a common feature of breast cancer (BC)." (PMID 36922677, 2023). "In contrast, other circulating lncRNAs (H19, SPRY4‐IT1, XIST, UCA1, AC026904.1, CCAT1, CCAT2, ITGB2‐AS, and AK058003) were significantly up‐regulated in breast cancer patients compared to controls." (PMID 36274054, 2023).